DPP4 (dipeptidyl peptidase 4)
Diseases named in the same sentence as DPP4 in open-access papers (continued):
Sharing a sentence is not in itself a finding about the gene and the disease.
infection (continued). "To test the possibility of using human DPP4 for infection, we used the human HOS cell line stably expressing human DPP4 and TMPRSS2 (HOS-hDPP4/TMPRSS2) as target cells for pseudovirus infection." (PMID 40740328, 2025). "The direct infection of endothelium, astrocytes, and pericytes, the three discrete cell types that comprise the BBB, is possible through ACE2 and DPP4, respectively." (PMID 38793666, 2024). "The results of our adult in vitro infection and RNA expression analyses demonstrated moderate expression of coronavirus receptors CD147 and DPP4 in the adult cortex." (PMID 35858406, 2022). "Specifically, while knockdown of BSG/CD147 or treatment with DPP4 inhibitor (vildagliptin) significantly reduces SARS-CoV-2 infection, conversely overexpressing BSG/CD147 or DPP4 increases infection in vitro." (PMID 35858460, 2022). "In this study, we used well-differentiated human primary airway epithelia as a model to explore how DPP4 distribution and abundance relate to MERS-CoV tropism and infection." (PMID 35059374, 2021). "Cell studies have identified DPP4 as a functional receptor for human coronavirus–Erasmus Medical Center (HCoV-EMC) and antibodies targeting DPP4 inhibited infection of primary cells by HCoV-EMC." (PMID 34830623, 2021). "Significant upregulation of IFN-β and IFN-λ was seen only at the later timepoints post infection (days 3–5), primarily in the HAE donors with above average DPP4 abundance." (PMID 35059374, 2021). "In this study, we investigated the variability in several pig genes (ACE2, ANPEP, DPP4 and TMPRSS2) that can serve as receptors or protease for priming the infection of coronaviruses." (PMID 33564056, 2021). "An infection assay on two of these clones revealed that MERS-CoV replication was fully blocked, while SARS-CoV-2 replicated in the DPP4-mutant organoids at control levels." (PMID 34535662, 2021). "Knowledge about the expression of ACE2 and TMPRSS2, as well as other potential entry genes of SARS-CoV-2, namely FURIN, DPP4, and BSG, is extremely important to understand the infection of SARS-CoV-2 and to find ways to prevent the infection." (PMID 33081421, 2020). "We compared major adverse cardiac cerebrovascular events (MACCEs) and mortality (overall, infection-related, and MACCE-related) of pioglitazone to that of dipeptidyl peptidase 4 inhibitors (DPP4-inhibitors) in patients with T2DM and ESRD." (PMID 33172034, 2020). "The infection with morbid and deadly human CoVs, MERS- and SARS-CoV, is mediated by the high-affinity interaction between viral RBD and respectively, dipeptidyl peptidase 4 (DPP4) and angiotensin-converting enzyme 2 (ACE2) in host cells." (PMID 32854433, 2020). "Implying a similar process after infection with SARS-Cov2, monocytes and T cells are infected with MERS-CoV via dipeptidyl peptidase 4 (DPP-4), while SARS-CoV infects primary human monocytes as well as dendritic cells." (PMID 33133024, 2020). "This high prevalence of MERS-CoV in camels is attributed to the abundance of the cellular dipeptidyl peptidase 4 (DPP4), which is responsible for binding with MERS-CoV spike protein to initiate the infection, in the URT epithelium of camels." (PMID 32630780, 2020). "The S protein of MERS-CoV uses Dipeptidyl peptidase 4 (DPP4/CD26) and carcinoembryonic antigen-related cell adhesion molecule 5 (CEACAM5) as attachment or entry receptors for infection." (PMID 33375175, 2020). "The S1 subunit comprises N-terminal domain (NTD) and receptor-binding domain (RBD) that recognizes and binds to dipeptidyl peptidase 4 (DPP4, also known as CD26) receptor on the host cell surface to initiate infection." (PMID 31329652, 2019). "As only few of the abundant number of CD4+ T cells at the site of infection express CXCR3, it seems plausible that the CXCL10/CXCR3 chemotactic axis is under regulation by DPP4 in active TB." (PMID 30026741, 2018).
infection (continued). "MERS-CoV initiates infection through the interaction between the receptor-binding domain (RBD) in S1 and the receptor dipeptidyl peptidase-4 (DPP4, also known as CD26)." (PMID 28906430, 2017). "To further confirm that IRAK-M, PPARγ and IL-10 were induced via the interaction of S glycoprotein with DPP4, we used siRNA approach to knock-down DPP4 in THP1 macrophages prior to infection." (PMID 28118607, 2017). "Using this rescued virus, we analyzed receptor molecules for infection and found that EjCoV-3 did not use DPP4 and ACE2, which are receptor molecules for MERS-CoV and SARS-CoV, respectively." (PMID 40525828, 2025). "Unlike SARS-CoV-2, MERS-CoV uses dipeptidyl peptidase-4 (DPP-4) as its functional receptor to enter cells and cause infection." (PMID 41169390, 2025). "While these findings suggest that EjCoV-3 may utilize ACE2 under certain conditions, our study clearly demonstrates that spike-mediated infection by EjCoV-3 occurs independently of both ACE2 and DPP4." (PMID 40525828, 2025). "It appears that DPP4 plays a small but noticeable role in BBB infection (and only in the absence of ACE2) since gliptin drugs have been demonstrated to directly interfere with the binding site exploited by the SARS-CoV-2 spike." (PMID 38793666, 2024). "Third, knocking down ACE2 in HUVECs, and DPP4 in astrocytes and pericytes diminishes but does not completely ablate infection." (PMID 38793666, 2024). "In conclusion, the BBB is susceptible to SARS-CoV-2 infection in multiple ways, including the direct infection of endothelium, astrocytes, and pericytes involving ACE2 and/or DPP4 and the blood-to-brain transcytosis, which is an event that does not require the presence of host receptors." (PMID 38793666, 2024). "Consistent with data from patients who received IFN treatment, plasma DPP4 concentrations, liver enzymes, and cytokine levels were reduced after resolution of infection with direct-acting antiviral therapy with or without ribavirin." (PMID 36472923, 2023). "MERS-CoV and SARS-CoV-2 infections in 293T were not inhibited by isotype control antibody; however, infection with MERS-CoV in the presence of the anti-DPP4 antibody showed a significant reduction, unlike SARS-CoV-2 where the infection persisted." (PMID 37808906, 2023). "We have studied if MERS-CoV, whose canonical receptor is dipeptidyl peptidase-4 protein (DPP4), could have DC-SIGN as an alternative receptor for cis or trans-infection." (PMID 37808906, 2023). "Further RWD studies with a larger sample size and an extended follow-up period is required to verify the current study findings and to evaluate long-term safety of DPP-4 inhibitors and SGLT-2 inhibitors in terms of new-onset infections when combined with insulin in later-stage T2DM patients." (PMID 37891260, 2023). "They predicted that the S1 domain of SARS-COV-2 S protein potentially interacts with the human CD26/DPP4 and suggested that SARS-COV-2 may share infection modes with that of SARS-CoV and MERS-CoV." (PMID 34239932, 2021). "Transfection of human ACE2 or CD26/DPP4 in nonsusceptible cells of different lineages or species permitted infection with SARS-CoV, SARS-CoV-2, or MERS-CoV, respectively." (PMID 34239932, 2021). "DPP4/CD26, a potential cofactor for SARS-CoV-2 infection, is also downregulated by apabetalone, with potential synergistic effects with ACE2 reductions that block cellular SARS-CoV-2 uptake and infection." (PMID 33919584, 2021). "In addition, several studies have been suggesting that the MERS-CoV receptor, dipeptidyl peptidase 4 (DPP4), can also be used by SARS-CoV-2 during infection." (PMID 33193377, 2020). "However, the spike protein encoded by MERS-CoV, despite its high similarly to the spike protein of SARS-CoV and SARS-CoV-2 viruses, recognizes CD26 (also known as dipeptidyl peptidase 4, DPP4) as a receptor for cellular entry and infection." (PMID 32660065, 2020).
infection (continued). "We found that the levels of DPP4 transcripts in infected cells did not decrease following infection of Efk cells with either W + or ΔORF5 MERS-CoV." (PMID 32350357, 2020). "Efk cells infected with W + MERS-CoV contained high levels of DPP4 transcripts, which did not decrease significantly in the 48 hrs following infection." (PMID 32350357, 2020). "We utilized an established transgenic mouse model of MERS-CoV pathogenesis for these studies where the murine ortholog of the human receptor, dipeptidyl peptidase 4 (DPP4) was humanized at residues 288 and 330 (288/330+/+ mice) to facilitate infection and pathogenesis reminiscent to that in humans." (PMID 31339932, 2019). "Notably, the mouse mAb G2 can greatly relieve the symptom of DPP4-transgenic mice infected following MERS-CoV infection and our 7D10-H can inhibit the infection of pseudotyped MERS-CoV in R26-hDPP4 mice." (PMID 31296843, 2019). "Although human DPP4 (hDPP4) has been identified as the receptor for MERS-CoV that mediates infection, mouse DPP4 (mDPP4) is not functional in this respect." (PMID 30142928, 2018). "Our study is descriptive, and the key claim that the abrogated CXCR3/CXCL10 axis is DPP4-mediated and occurring at the site of infection remains circumstantial without direct confirmation." (PMID 30026741, 2018). "Given also that the PREDICT/PDF-2180 spike does not use DPP4 and is seemingly not competent for human infection, we further suggest that the recombination event was the critical factor driving the emergence of MERS-CoV." (PMID 28377531, 2017). "In contrast, DPP4 was barely detected in the respiratory tract of sheep, probably accounting for the lack of infection reported here." (PMID 27901465, 2017). "The NHPs develop transient infection but do not die from infection, whereas transgenic mice overexpressing DPP4 die from MERS-CoV infection." (PMID 27050368, 2017). "Small animals do not naturally express a functional form of the dipeptidyl peptidase 4 (DPP4) receptor; however, transgenic mice expressing human DPP4 are susceptible to infection." (PMID 29083948, 2017). "Upon DPP4 inhibition, no increase in CVD was observed in T2DM patients, but risk of infection was reduced." (PMID 29253907, 2017). "Similar to other studies using MERS-CoV-resistant (non-bat) cell lines transfected with CD26/DPP4, expression of human CD26/DPP4 in resistant bat cells rendered these cell lines susceptible to infection." (PMID 25409519, 2014). "The expression of DPP4 and SPC proteins, as well as the presence of microvilli, but most importantly the presence of lamellar bodies inside the hLORGs, suggest that we have obtained an in vitro model of relatively mature AT2-like cells, useful as infection targets in our investigations." (PMID 35406799, 2022). "Embryos also displayed evidence of infection by reporter virions pseudotyped with the S protein from SARS-CoV-1 (which similarly uses ACE2 for entry) but not with the S protein from MERS-CoV (which uses DPP4 for entry)." (PMID 36104397, 2022). "Human aminopeptidase N (APN) is involved in the infection by HCoV-229E; 9-O-acetylated sialic acid (9-O-Ac-Sia) receptor for HCoV-OC43 and HCoV-HKU1; angiotensin-converting enzyme 2 (ACE2) for HCoV-NL63, SARS-CoV-1, and SARS-CoV-2; dipeptidyl peptidase 4 (DPP4) for MERS-CoV." (PMID 33668428, 2021). "During the infection of SARS‐CoV‐2, DPP‐4 might play important roles." (PMID 32713161, 2020). "If CD26/DPP4-positive cells of bats become infected with MERS-CoV and if subsequently the receptor surface expression is downregulated as we observe in our experiments, a persistent infection could be established." (PMID 25409519, 2014). "Our results showed that EjCoV-3 does not utilize ACE2 and DPP4, cell entry receptors for SARS-CoV and MERS-CoV, as a means of infection." (PMID 40525828, 2025).
infection (continued). "In human infection, Middle East respiratory virus (MERS-CoV) uses the host cell receptor dipeptidyl peptidase 4 (DPP4), of which ferret DPP4 is not conducive as a MERS-CoV receptor." (PMID 33468694, 2021). "Unlike SARS-CoV-2 and SARS-CoV-1, MERS-CoV required dipeptidyl peptidase-4 (DPP-4) as its functional receptor to enter cells and evoke infection in cells." (PMID 32403255, 2020). "Since DPP4 was not expressed in T. pachypus cells while this bat species hosts Ty-BatCoV HKU4, a close relative of MERS-CoV which can utilize hDPP4 for cell entry, we overexpressed Tp-DPP4 in T. pachypus lung and kidney cells for infection by MERS-CoV." (PMID 30531999, 2018). "The observation that cultures continued to release significant virion amounts on day 63 post-inoculation, but also exhibited low to absent CD26/DPP4 cell-surface expression, is consistent with receptor downregulation as one mechanism for persistent infection with MERS-CoV in our experiments." (PMID 25409519, 2014). "Recent studies have highlighted that alternate receptors may be used for SARS-CoV-2 entry to the cells of the CNS, with neuropilin-1, CD147 and DPP4 reported as potential SARS-CoV-2 entry factors for astrocytes, and that TMPRSS2 is not required for infection of neurons." (PMID 38995681, 2024). "However, DPP4 and CD147 may not be the sole receptors that mediate infection since a low level of infection can persist after both are inhibited." (PMID 35858406, 2022).
cardiovascular disease (111 papers, 2013 to 2026). "Serum samples from persons with high risk for cardiovascular disease contained high levels of DPP4-regulated complement and coagulation factors." (PMID 37097759, 2023). "Dipeptidyl peptidase 4 (DPP4) levels are associated to metabolic and cardiovascular diseases in humans; initial evidence reported a relationship between DPP4 and chronic liver diseases." (PMID 32852705, 2021). "Further large-scale studies are necessary to establish these associations and determine the role of DPP4 and nesfatin-1 in the pathogenesis of cardiovascular disease." (PMID 34389003, 2021). "SGLT2 inhibitors cause a greater reduction than dipeptidyl peptidase-4 (DPP-4) inhibitors in body weight and the risk of cardiovascular disease." (PMID 32351447, 2020). "The cardiovascular safety of GLP-1 RAs, SGLT-2 inhibitors, and DPP-4 inhibitors has been investigated in RCTs that primarily included patients with established cardiovascular disease or with multiple risk factors." (PMID 32631337, 2020). "There is lack of solid information on differences in the therapeutic effects of SGLT2 inhibitors and DPP4 inhibitors on multiple risk factors for cardiovascular diseases." (PMID 29895330, 2018). "In addition, we surveyed human serum samples from the Baltimore Longitudinal Study of Aging (BLSA) from people aged 50 to 65 with low and high Framingham risk scores (FRS), which estimate the risk of cardiovascular disease, for circulating levels of DPP4." (PMID 37097759, 2023). "This study sought to determine whether a differential risk of cardiovascular disease (CVD) exists for the combination of a dipeptidyl peptidase-4 (DPP-4) inhibitor plus metformin versus a sulfonylurea derivative plus metformin or pioglitazone plus metformin." (PMID 25992614, 2015). "Thus, the inhibition of plasma DPP4 activity by DPP4 inhibitors could represent a common mechanism underlying their pleotrophic effects on inflammatory atherosclerosis-based cardiovascular disease." (PMID 27654253, 2016). "DPP-4 was widely expressed in the cardiovascular tissues and participated in the physiopathologic process of various cardiovascular diseases." (PMID 40810069, 2025). "Conversely, through a number of pathways, DPP-4 inhibitors directly control the development and course of cardiovascular disorders." (PMID 40429343, 2025). "Subgroup analyses indicated that prior cardiovascular disease modified the effect of high‐affinity sulfonylureas versus DPP‐4 inhibitors (P for interaction = 0.012)." (PMID 41017568, 2025). "On the other hand, additionally, DPP-4 inhibitors directly regulate the occurrence and progression of cardiovascular disorders through a variety of mechanisms." (PMID 40771927, 2025). "In contrast, DPP-4 inhibitors exhibit significantly lower efficacy in the prevention and management of cardiovascular diseases despite some evidence of modest improvements in vascular and endothelial function." (PMID 40725024, 2025). "Due to the intricate relationship between glucose regulation and cardiovascular diseases (CVDs), DPP-4 inhibitors have attracted attention for their cardiovascular safety and efficacy." (PMID 40212217, 2025). "Abbreviations- CVD: cardiovascular disease; DPP4 inhibitors: dipeptidyl peptidase four inhibitors; GLP1RA: glucagon-like peptide 1 receptor agonist; SGLT2 inhibitors: sodium-glucose cotransporter-2 inhibitors." (PMID 39737272, 2024). "Substance P and neuropeptide Y are important substrates of DPP4 that can mediate various detrimental effects in cardiovascular diseases." (PMID 35884882, 2022). "DPP4 inhibitors exert pleiotropic effects on cardiovascular diseases directly through complicated cellular mechanisms." (PMID 34489872, 2021). "This review highlights the function of DPP4 inhibitors in type 2 DM, and in treating cardiovascular diseases, with special emphasis on arteriogenesis." (PMID 30360455, 2018).